PTGFRN (prostaglandin F2 receptor inhibitor)
Description:
Inhibits the binding of prostaglandin F2-alpha (PGF2-alpha) to its specific FP receptor, by decreasing the receptor number rather than the affinity constant. Functional coupling with the prostaglandin F2-alpha receptor seems to occur (By similarity). In myoblasts, associates with tetraspanins CD9 and CD81 to prevent myotube fusion during muscle regeneration (By similarity).
Synonyms: CD9P-1; EWI-F; CD315; FPRP; KIAA1436; FLJ11001; SMAP-6
Tractability: Antibody: UniProt predicts a signal peptide or a membrane-spanning region. PROTAC: ubiquitination databases record sites on it; its protein half-life has been measured.
Gene: Protein-coding gene on chromosome 1 (116,909,894 to 116,990,358, forward strand). Ensembl gene ENSG00000134247.
Subcellular location: Endoplasmic reticulum membrane; Golgi apparatus, trans-Golgi network membrane
Gene Ontology:
Molecular function: protein binding
Biological process: myoblast fusion involved in skeletal muscle regeneration
Cellular component: cell surface; membrane; endoplasmic reticulum membrane; Golgi apparatus
Genetic constraint (gnomAD): Loss-of-function variants: 32 observed, 77.79 expected, observed/expected ratio (o/e) 0.41, 90% interval 0.31 to 0.55. The upper end of that interval is the gene's LOEUF score, 0.55, which puts it in group 2 of 6, group 1 being the genes least tolerant of losing a copy. Missense variants: 1,023 observed, 1,162.4 expected, observed/expected ratio (o/e) 0.88, 90% interval 0.83 to 0.93. Synonymous variants: 508 observed, 489.52 expected, observed/expected ratio (o/e) 1.04, 90% interval 0.96 to 1.12.
Homologues: Orthologues: chimpanzee PTGFRN (99% identical), macaque PTGFRN (99% identical), rabbit PTGFRN (91% identical), mouse Ptgfrn (90% identical), rat Ptgfrn (89% identical), pig PTGFRN (89% identical), dog PTGFRN (87% identical), guinea pig PTGFRN (84% identical), tropical clawed frog ptgfrn (41% identical), zebrafish ptgfrnb (34% identical), zebrafish ptgfrna (30% identical). Paralogues in human: IGSF3 (23% identical), CD101 (23% identical), IGSF8 (17% identical), VSTM4 (6% identical), VSTM2A (6% identical).
Diseases named in the same sentence as PTGFRN in open-access papers:
PTGFRN is named in the same sentence as 42 diseases in open-access papers, as found by Europe PMC text mining. Sharing a sentence is not in itself a finding about the gene and the disease. The quoted sentences say what the papers report.
glioblastoma (8 papers, 2021 to 2025). The most malignant astrocytic tumor (WHO grade IV). "Notably, PTGFRN is overexpressed in glioblastoma multiforme and is associated with poor survival." (PMID 35606887, 2022). "The inhibition of PTGFRN lifted the radiosensitivity of glioblastoma tumors and declined tumor growth." (PMID 37427097, 2023). "These authors also determined that inhibition of PTGFRN by shRNA also increased the radiosensitivity of glioblastoma tumors, as well as decreased cell proliferation and tumor growth." (PMID 33503070, 2021). "Additionally, PTGFRN expression was also found to have prognostic value for glioblastoma patients, and imparted a resistance to radiation sensitivity of these cancers." (PMID 40551322, 2025). "Prostaglandin F2 receptor negative (PTGFRN) regulator is overexpressed in glioblastoma multiforme and associated with poor survival, downregulates its expression of radiosensitized cancer cells, and effectively slows down the rate of cell proliferation and tumor growth." (PMID 35942407, 2022). "When comparing metastatic cancer cells to their non‐metastatic counterparts, PTGFRN mRNA and protein expression have been reported to be significantly upregulated in some lung cancers (NCI‐H460), melanomas (MDA‐MB‐435), and glioblastomas (U87MG and A172)." (PMID 40551322, 2025). "High expression of prostaglandin F2 receptor inhibitor (PTGFRN), a type I (single pass) transmembrane Ig superfamily of CAM, could protect cells from apoptosis, thereby promoting growth and migration in glioblastoma cells." (PMID 38069077, 2023).
lung carcinoma (6 papers, 2011 to 2025). "More importantly, PTGFRN expression was demonstrated to be associated with the metastatic status of lung cancer." (PMID 37427097, 2023). "For LC-cell line markers, the A549 line-specific EV proteins CD109 and PTGFRN were found to be metastasis-associated in lung cancer." (PMID 32916986, 2020). "In addition, in vivo, PTGFRN has been shown to be involved in the tumor growth of lung cancer." (PMID 40047938, 2025). "Our results were further strengthened by the recent reports wherein PTGFRN was found to be conferring resistance to radiation via PI3K-AKT signaling in GBM and its expression correlated with metastatic capacity in lung cancer." (PMID 35690717, 2022).
colorectal cancer (3 papers, 2012 to 2022). A primary or metastatic malignant neoplasm that affects the colon or rectum. "PTGFRN exhibits gene fusion (PTGFRN-NOTCH2) in colorectal cancer and point mutations in small cell lung cancer." (PMID 35690717, 2022). "In addition, we examined the PTGFRN-NOTCH2 gene fusion in additional ten samples by RT-PCR, but none of them showed the gene fusion, suggesting that the PTGFRN-NOTCH2 might be a rare gene fusion in colorectal cancer." (PMID 22905095, 2012).
glioma (3 papers, 2022 to 2025). A benign or malignant brain and spinal cord tumor that arises from glial cells (astrocytes, oligodendrocytes, ependymal cells). "Recently, silencing of PTGFRN in glioma cells in vitro downregulates cell proliferation, migration, invasion, cell cycle progression, and apoptosis, suggesting its oncogenic role in gliomas." (PMID 40047938, 2025). "We observed that PTGFRN is required for cell growth, migration, invasion, progression of the cell cycle, and evading apoptosis in glioma cells." (PMID 35690717, 2022). "PTGFRN was also found to be higher in glioma stem-like cells (GSCs) than the matched differentiated glioma cells (DGCs) and is required for GSC growth and survival." (PMID 35690717, 2022). "We chose glioma cell lines based on different PTGFRN expression levels, high (T98G), moderate (U373 and U251), and low (U87), for further studies." (PMID 35690717, 2022). "Silencing of PTGFRN in glioma cell lines was achieved by the stable expression of short hairpin RNA (shRNA) against the PTGFRN gene." (PMID 35690717, 2022). "We found that PTGFRN expression is high in glioma tissues, cell lines, and GSCs, and its increased expression correlates with poor patient survival, corroborating previous reports." (PMID 35690717, 2022). "The poor prognostic indicator PTGFRN was chosen to study its role in glioma." (PMID 35690717, 2022). "Silencing PTGFRN significantly reduced cell proliferation, colony formation, anchorage-independent growth, migration, and invasion in U373, U343, T98G, U251, and U87 glioma cells." (PMID 35690717, 2022). "Prostaglandin F2 receptor inhibitor (PTGFRN) is a type I (single pass) transmembrane Ig superfamily CAM, which was shown to be upregulated in several cancers, including glioma." (PMID 35690717, 2022). "We found that silencing PTGFRN reduced ERK, AKT, and mTOR signaling in glioma cell lines." (PMID 35690717, 2022).
medulloblastoma (3 papers, 2021 to 2025). A malignant, invasive embryonal neoplasm arising from the cerebellum. "Among the cancer tissues examined, we investigated PTGFRN expression in mesothelioma and in medulloblastoma, which are two cancers with unmet needs for targeted therapies." (PMID 40551322, 2025). "The identification of PTGFRN as an ADC target is the first step in developing specific therapy for solid tumour cancers that express PTGFRN, such as medulloblastoma and mesothelioma." (PMID 40551322, 2025). "Our laboratory has previously identified PTGFRN as being expressed and internalized in epidermoid carcinoma, paediatric medulloblastoma, and mesothelioma cancer cells." (PMID 40551322, 2025). "The identification of PTGFRN carried out with spindle cell carcinoma cells was confirmed in human head and neck cancer A431 and medulloblastoma DAOY cells by immunoprecipitation with the 33B7 antibody followed by mass spectrometry analysis (Data not shown)." (PMID 33503070, 2021). "Furthermore, an antibody–drug conjugate of PTGFRN conjugated with saporin has been shown to be effective against PTGFRN-positive cancer cells, such as epidermoid carcinoma, spindle carcinoma, and medulloblastoma." (PMID 40047938, 2025). "The immunohistochemistry we performed indicated that PTGFRN expression was undetectable in various non‐cancerous tissues, whereas PTGFRN expression was significantly elevated in several cancers, including mesothelioma and medulloblastoma." (PMID 40551322, 2025). "The resulting antibody drug conjugate (8C7‐ADC) was first examined in vitro for its ability to inhibit the proliferation of PTGFRN‐expressing cell lines such as epidermoid carcinoma (A431), biphasic mesothelioma (MSTO‐211H), and paediatric medulloblastoma (DAOY)." (PMID 40551322, 2025). "Since we had previously shown that PTGFRN was expressed in the human mesothelioma cell line MSTO‐211H and in the human medulloblastoma cell line DAOY, we examined PTGFRN expression by IHC in tissue sections from patient‐derived mesothelioma and medulloblastoma tissue arrays." (PMID 40551322, 2025).
epidermoid carcinoma (2 papers, 2025). "When screening various head & neck and kidney cancer tissue samples, Squamous Cell Carcinoma, Melanoma, Papillary Renal Cell Carcinoma, Clear Cell Carcinoma, and Pancreatic Duct Adenocarcinoma showed a strongly detectable level of PTGFRN expression." (PMID 40551322, 2025).
mesothelioma (2 papers, 2021 to 2025). A usually malignant and aggressive neoplasm of the mesothelium which is often associated with exposure to asbestos. "Pleural mesothelioma tissue showed modestly elevated expression of PTGFRN, whereas pericardial mesothelioma tissue, which is commonly found when pleural mesothelioma metastasises, showed a significant increase in PTGFRN expression." (PMID 40551322, 2025). "Conversely, overexpression of PTGFRN in mesothelioma MSTO‐211H resulted in an increase in proliferation, migration, clonogenicity, and Spheroid formation in 3D culture." (PMID 40551322, 2025). "An ADC that targets increased expression in advanced lesions of a biomarker like PTGFRN in mesothelioma would be an invaluable tool to develop new treatments for patients suffering from these advanced‐stage cancers, along with the availability of a biomarker to identify patients." (PMID 40551322, 2025).
alcohol fatty liver disease (1 paper, 2021). "PTGFRN has been shown to affect a wide range of biological processes such as fertilization, migration, and accumulation of lipids in preadipocytes, extracellular vesicle bioactivity, non-alcohol fatty liver disease, and Alzheimer’s disease." (PMID 33503070, 2021).
amyloid (1 paper, 2020). "In addition, the PTGFRN showed a moderate correlation with amyloid plaque (rho = 0.404, p = 0.027) and tangle scores (rho = 0.500, p = 0.005) in AD, MCI and CTRL." (PMID 32854315, 2020).
cystic teratomas of the ovary (1 paper, 2022). "Among the prevalent mutated genes, 7 with the same variant in exons with changes in protein coding are important for the development of mature cystic teratomas of the ovary: PTGFRN, DUSP5, MPP2, PHLDA1, PRR21, GOLGA6L2, and KRTAP4-2." (PMID 36289533, 2022).
head and neck squamous cell carcinoma (1 paper, 2012). A squamous cell carcinoma that arises from any of the following anatomic sites: lip and oral cavity, nasal cavity, paranasal sinuses, pharynx, larynx, and salivary glands. "Therefore, we inferred that the gene fusion PTGFRN-NOTCH2 in this study appeared to be more like a loss-of-function mutations, consistent with those recently described for myeloid leukemia, head and neck squamous cell carcinoma." (PMID 22905095, 2012).
liver disease (1 paper, 2013). "We found significant fold changes for SPINK1, LEF1, TSPAN8, SPP1, OR2I1P and PTGFRN comparing HH-HCC with HH-liver disease and normal liver (p<0.05, one-way Anova)." (PMID 23527199, 2013).
metastatic cancers (1 paper, 2021). A carcinoma which has spread from the original site of growth to another anatomic site. "Due to the fact that PTGFRN is found to be further upregulated in metastatic cancers, an ADC would be more attractive as a potential targeted therapy." (PMID 33503070, 2021). "Previous research has shown that at the mRNA level, PTGFRN expression is increased in metastatic cancer cells." (PMID 33503070, 2021).
pediatric medulloblastoma (1 paper, 2021). "In summary, PTGFRN is a cell-surface protein that is upregulated in certain cancer types, including head and neck (A431) and, notably, pediatric medulloblastoma (DAOY), an aggressive cancer with limited therapeutic options." (PMID 33503070, 2021).
pleural tumour (1 paper, 2025). "Interestingly, PTGFRN IHC in patients' samples showed negative staining in a healthy lung sample, mild PTGFRN expression in a pleural tumour, but significantly increased PTGFRN staining after invasion of the pericardium." (PMID 40551322, 2025).
schizophrenia (1 paper, 2021). A major psychotic disorder characterized by abnormalities in the perception or expression of reality. "While additional investigation needs to be done to elucidate the exact role the PTGFRN protein plays in these processes, the PTGFRN gene itself has also been identified as a possible predictor for risperidone activity in patients with schizophrenia." (PMID 33503070, 2021).
tumor (21 papers, 2011 to 2025). "Prostaglandin F2 receptor negative regulator (PTGFRN), a tumorigenesis-related gene, was associated with interleukin (IL)-12-mediated tumor recognition and killing efficacy for drugs." (PMID 37405952, 2023). "Moreover, PTGFRN has been found to be associated with biological functions that play important roles in tumor development." (PMID 33503070, 2021). "We observed a dose‐dependent and statistically significant reduction in tumour growth rate for the three PTGFRN‐expressing cells bearing mice treated with the 8C7‐ADC compared to the control ADC." (PMID 40551322, 2025). "IL-12 was expressed on EV surface by conjugating with PTGFRN, and these EVs were shown to suppress tumor growth by increasing tumor antigen-specific CD8+ T cells." (PMID 38796692, 2024). "These exosomes, which are produced by human kidney embryonic HEK293 cells overexpressing prostaglandin F2 receptor negative regulator (PTGFRN), proved to have a tropism for tumor-associated macrophages." (PMID 36831450, 2023). "PTGFRN was also shown to be overexpressed in tumors and was recognized as an essential part of angiogenesis, which is a necessary process in tumor proliferation." (PMID 37427097, 2023). "We found that PTGFRN to be upregulated in GBM tumor samples and cell lines with a significant poor prognostic correlation with patient survival." (PMID 35690717, 2022). "Toward improved tumor targetability, IL12 was displayed on exosome surface via fusion with the exosome surface protein PTGFRN, and the resultant exosome (exoIL12) conveyed tumor-restricted pharmacology that led to prolonged tumor retention and immune memory." (PMID 36119094, 2022). "We observed that anti-tumor activity was correlated with PTGFRN density on EVs with PTGFRN−/− EVs having minimal anti-tumor activity." (PMID 33888863, 2021). "As proof-of-concept, we show that an antibody-drug conjugate (ADC) of 33B7 conjugated with saporin was effective in inhibiting in vitro cell proliferation and in vivo tumor growth of PTGFRN-positive cancer cells A431 and AGSCC-3 cells." (PMID 33503070, 2021). "al, PTGFRN was found to be essential for angiogenesis, a necessary process in tumor growth." (PMID 33503070, 2021). "A genetic construct based on PTGFRN linked with the self‐peptides or other “do not eat me” motifs by the cleavable linker suitable to be degraded by tumor over‐expressed proteases could decrease off‐tumor internalization of engineered therapeutic sEV." (PMID 36684102, 2023). "PTGFRN was experimentally validated to exhibit pro-migratory and pro-proliferative functions in GBM, highlighting its role in tumor invasion." (PMID 40565099, 2025). "We then examined the effect of 8C7‐ADC (0.4 mg/kg and 1.6 mg/kg) on the tumour growth of DAOY cells, which also displayed high expression of PTGFRN." (PMID 40551322, 2025). "MSTO‐211H cells, which express lower levels of PTGFRN, were treated with 8C7‐ADC at 1 and 4 mg/kg, resulting in a dose‐dependent tumour inhibition of 32% and 63%, respectively." (PMID 40551322, 2025). "Among all genes in the focal amplifications, only five (TBX15, NOTCH2, PTGFRN, CNN3, and PHGDH) showed appreciably higher expression levels than those observed in tumor samples from the TCGA database." (PMID 28977029, 2017). "Treatment of mice bearing A431 tumours with a 33B7‐Saporin conjugate showed no obvious signs of off‐target toxicity to any mouse organs, supporting PTGFRN's potential as a viable ADC cancer target." (PMID 40551322, 2025). "Genetic engineering involves the fusion of tumor-targeting or tumor-penetrating peptides with transmembrane proteins, including LAMP2B, PDGFR, PTGFRN, CD63, CD9, and CD81, on EVs and the expression of the fused protein in donor cells, which produce EVs with the functional peptides on the surface." (PMID 38796692, 2024). "Our results suggest that the high expression levels of SPP1 and PTGFRN may be a key component in the LUAD early invasions and can lead to a more malignant tumor condition." (PMID 37427097, 2023).
tumor (continued). "Since the AGSCC3 and A431 cell lines showed the highest level of PTGFRN expression, as well as the highest response to 33B7-ADC, these cell lines were selected to examine the effect of 33B7-ADC on in vivo tumor growth in mouse xenograft model when compared to isotype control ADC." (PMID 33503070, 2021). "In addition, we compared the in vivo activity of different EVs (WT, PTGFRN−/− and PTGFRN+/+) loaded with equal amounts of CDN in the B16F10 tumor model." (PMID 33888863, 2021). "Tumours that displayed high PTGFRN expression, such as A431 and DAOY tumours, exhibited a high reduction in tumour growth with no obvious signs of off‐target toxicity in response to the 8C7‐ADC, demonstrating its efficacy." (PMID 40551322, 2025). "We thus separately designed a pair of primers that coordinate with the first intron of PTGFRN and the exon region of NOTCH2 to confirm this fusion in normal, adjacent non-tumor and cancer tissue by RT-PCR." (PMID 22905095, 2012).